MB (myoglobin)
Diseases named in the same sentence as MB in open-access papers (continued):
Sharing a sentence is not in itself a finding about the gene and the disease.
acute kidney injury (continued). "Although the release of myoglobin (molecular weight 17.2 kDa) into the blood is associated with the progression to acute kidney injury, there is no established method to prevent it." (PMID 40114230, 2025). "Rhabdomyolysis often worsens significantly with physical activity/exercise or in the presence of other stressors (e.g., statin use), leading to elevated serum CK and myoglobin levels, myoglobinuria, and potential progression to acute kidney injury, hyperkalemia, and metabolic acidosis." (PMID 39834954, 2024). "This phenomenon has also been observed in studies of myoglobin-induced acute kidney injury." (PMID 38783935, 2024). "Rhabdomyolysis is a condition characterized by the breakdown of muscle tissue leading to the release of muscle contents such as myoglobin and creatine kinase (CK) into the bloodstream, which can result in severe complications, including acute kidney injury (AKI) and electrolyte imbalances." (PMID 39280413, 2024). "Alkalizing urine can prevent myoglobin deposits from forming, which can lead to renal failure." (PMID 39635585, 2024). "Particularly, the release of myoglobin induces severe oxidative damage because the heme portion induces lipid peroxidation and renal tubular injury, which is one of the main factors in the development of acute kidney injury (AKI)." (PMID 38282162, 2024). "In addition, sometimes the myoglobin froms myoglobin casts that are large enough to obstruct renal tubular epithelial cells and can lead to an acute kidney injury in the longer term (after the race has finished), and these dogs are lost to follow-up." (PMID 38476168, 2024). "Acute kidney injury (AKI), defined as a rapid increase in serum creatinine, decrease in urine output, or both, is a common clinical syndrome caused by multiple factors, including renal ischemia, sepsis, toxic effects from drugs, and pigment-related injury from myoglobin or hemoglobin." (PMID 37122024, 2023). "An intramuscular injection of glycerol is performed in the two limbs to induce rhabdomyolysis, thereby releasing myoglobin from the muscles into the bloodstream and leading to subsequent acute kidney injury related to hypovolemia and direct toxicity of myoglobin on renal tubules." (PMID 35857494, 2022). "However, we reported strong nuclear PAX8 expression in proximal tubular cells in acute kidney injury provoked by myoglobin casts tubular obstruction." (PMID 36140438, 2022). "We present this case of coronavirus disease 2019-associated acute kidney injury with rhabdomyolysis—with noteworthy renal biopsy findings demonstrating myoglobin cast nephropathy—to add to the limited literature on coronavirus disease 2019-related acute kidney injury and rhabdomyolysis." (PMID 36578087, 2022). "As the major crotoxin-induced product into the circulation, myoglobin is responsible for inducing renal vasoconstriction, formation of intratubular casts, and the direct toxicity to kidney tubular cells, which can be followed by acute kidney injury (AKI)." (PMID 34168642, 2021). "Myoglobin (MYO)–induced acute kidney injury (AKI) is one of the most severe complications of RM." (PMID 34124093, 2021). "Myoglobin is excreted primarily by the kidney, and carries a risk of acute kidney injury which was however not seen in the CONTEXT study." (PMID 33292164, 2020). "Based on the findings of renal failure and loin pain after exercise, minor elevation in CK and myoglobin, hypouricemia, and increase in FEUA as well as the MRI findings of bilateral renal swelling and cuneiform low-signal areas, we made a diagnosis of RHUC and ALPE." (PMID 31771519, 2019). "This suggests a decisive role of the seven genetic polymorphisms included in this investigation on the leakage of intramuscular proteins into the blood stream during muscle-damaging exercise that ultimately can affect the development of myoglobin-induced renal failure." (PMID 28257486, 2017).
acute kidney injury (continued). "Myoglobin levels are predictive of development of compartment syndrome and acute renal failure." (PMID 28555191, 2017). "Kidney damage by myoglobin leads to acute kidney injury (AKI)." (PMID 28395668, 2017). "When skeletal muscle is damaged, myoglobin and other intracellular proteins leak into the circulatory system, resulting in myoglobinuria (tea-colored urine), and if this is sufficiently severe it can result in acute kidney injury (AKI)." (PMID 26412311, 2015). "The myoglobin then began to collect resulting in acute renal failure." (PMID 26693360, 2015). "Although myoglobin is not nephrotoxic per se, it is the true pathogenic factor in rhabdomyolysis-induced acute kidney injury." (PMID 23889764, 2013). "Massive muscular contraction following electric shock may lead to release of myoglobin, and renal failure may be precipitated by this." (PMID 22666596, 2012). "CVVH has more recently been used in a single case of myoglobin-induced renal failure." (PMID 15774055, 2005). "SHF hemofiltration achieved a much greater clearance of myoglobin than conventional hemofiltration, and it may provide a potential modality for the treatment of myoglobinuric acute renal failure." (PMID 15774055, 2005). "A suggestive history and laboratory results, including elevated levels of lactate dehydrogenase, CPK, myoglobin, and hyperphosphatemia, along with an acid-base imbalance in the presence of acute kidney injury (AKI), comprise the diagnosis of rhabdomyolysis." (PMID 39036240, 2024). "In particular, the release of myoglobin drives the major clinical complication of rhabdomyolysis, acute kidney injury (AKI)." (PMID 38536468, 2024). "Free circulating myoglobin can induce acute kidney injury (AKI) through tubular obstruction, direct tubular epithelial injury, or vasoconstriction." (PMID 38696335, 2024). "The acute kidney injury (AKI) is a result of both the hypovolaemia and the nephrotoxicity of myoglobin, urate and phosphate released from cells." (PMID 39708229, 2024). "This pathological process can lead to severe complications, such as acute kidney injury (AKI), due to the nephrotoxic effects of myoglobin and other intracellular proteins." (PMID 39086784, 2024). "The released myoglobin can accumulate in the kidneys and lead to acute kidney injury (AKI) and, in severe cases, renal failure." (PMID 38792394, 2024). "There was a positive correlation between the development of acute kidney injury (AKI) and myoglobin, serum lactate, and uric acid levels (r = 0.372, p = 0.003; r = 0.307, p = 0.016; r = 0.428, p = 0.001, respectively)." (PMID 38378483, 2024). "Myoglobin release plays a pivotal role in the pathophysiological mechanisms behind rhabdomyolysis related organ dysfunction particularly acute kidney injury (AKI)." (PMID 39085790, 2024). "Myoglobin released by rhabdomyolysis (RM) is considered to be involved in pathogenesis of kidney disease caused by crush injury, but whether high level of serum myoglobin predisposes patients to acute kidney injury (AKI) and its molecular mechanisms are still unclear in exertional heatstroke (EHS)." (PMID 37408574, 2023). "The accumulation of myoglobin can lead to an acute kidney injury (AKI) up to the requirement of dialysis." (PMID 37728069, 2023). "One is the well-known acute renal failure due to myoglobin, and the other is acute renal failure with severe back pain that develops after anaerobic exercise, which may not be due to myoglobin or may be induced by myolysis of type 2 muscle fibers due to anaerobic exercise." (PMID 35327453, 2022). "The development of acute kidney injury (AKI) is among the most serious complications, which is driven by myoglobin nephrotoxicity, oxidative stress, and inflammation." (PMID 33240909, 2020). "Release of muscle cell contents, including creatine kinase (CK) and myoglobin, can lead to fatal complications, including disseminated intravascular coagulation (DIC), arrhythmias, and renal failure." (PMID 41728554, 2026).
acute kidney injury (continued). "Rhabdomyolysis can lead to acute kidney injury (AKI), primarily due to myoglobin-induced tubular damage." (PMID 39347295, 2024). "Elevated myoglobin indicates the severity of RM, which can result in life-threatening complications, including acute kidney injury (AKI), hyperkalemia, hypocalcemia or hypercalcemia, metabolic acidosis, hyperuricemia, hyponatremia, hypovolemic shock, and cardiac dysrhythmias." (PMID 36532745, 2022). "Myoglobin-induced acute kidney injury (AKI) is one of the most severe complications of RM." (PMID 34124093, 2021). "Myoglobin and creatine kinase (CK) are both established markers of muscle injury but their hospital admission values have never been compared to predict post-traumatic acute kidney injury (AKI)." (PMID 34559325, 2021). "The leakage of muscle-cell contents including electrolytes, myoglobin, and Creatine Phosphokinase (CK) into the blood stream has toxic effects on the kidneys in a number of ways and may lead to acute kidney injury (AKI)." (PMID 28003911, 2016). "In the English literature there have been a number of cases reported of renal failure in EBV infection primary or secondary due to rhabdomyolysis and the subsequent acute tubular necrosis because of the released myoglobin." (PMID 18840267, 2008). "Patients who developed acute kidney injury had higher level of perioperative serum myoglobin than patients without acute kidney injury." (PMID 35273980, 2022). "Thus, renal vasoconstriction, the formation of intratubular casts and direct toxic effect of myoglobin on the tubule cells might lead to acute kidney injury (AKI) and the clinical picture of the “crush kidney”." (PMID 33509234, 2021). "In contrast to renal failure, there is no research focusing on the direct effect of myoglobin on the liver." (PMID 33684174, 2021). "Although all conservative therapeutic options should be exhausted to avoid a crush kidney, acute renal failure can usually not be avoided, especially at such high myoglobin concentrations." (PMID 33509234, 2021). "However, the correlation between serum myoglobin and acute kidney injury in such patients had not been established." (PMID 35273980, 2022). "After anaerobic exercise, such as sprinting, an acute kidney injury not related to myoglobin may develop." (PMID 31771519, 2019). "Acute kidney injury (AKI) may occur as a consequence of prolonged ischemia or exposure to toxins, either exogenic (the most frequently encountered ones in practice being contrast agents and various medications such as aminoglycosides or cisplatin) or endogenic (myoglobin, uric acid etc.)." (PMID 40722862, 2025). "It is, however, unusual to have acute kidney injury with normal creatine phosphokinase (CPK) and negative urine myoglobin." (PMID 41694166, 2026).
myocardial infarction (78 papers, 2008 to 2025). Gross necrosis of the myocardium, as a result of interruption of the blood supply to the area, as in coronary thrombosis. "Cardiac biomarkers, such as troponin, CK-MB, and myoglobin, remain standard laboratory measures for detecting acute myocardial infarction and ischemia, although their diagnostic and prognostic utility continues to be critically evaluated and debated." (PMID 41283479, 2025). "The isoenzyme activity of creatine kinase-MB can help to identify any kind of cardiac damage, and serves as an early diagnostic marker for myocardial infarction." (PMID 39598433, 2024). "Myoglobin is one of the well-known and early diagnostic biomarkers of acute myocardial infarction (AMI) that can be detected within three hours after the onset of symptoms." (PMID 25530617, 2014). "For example, by utilizing both biomarkers such ascTnI in combination with myoglobin could improve the diagnostic accuracyfor a second heart attack, even though myoglobin lacks specificityas a CVD marker and has a short half-life of 10–20 min." (PMID 39296866, 2024). "Recently, a meta-analysis of PYGB showed that it had moderate diagnostic accuracy for myocardial infarction (MI) and was superior to CK-MB and myoglobin." (PMID 38334681, 2024). "In addition, patients with HFRS can also experience acute cardiovascular events such as acute myocardial infarction and stroke, indicating that the increased levels of myocardial injury indicators such as creatine kinase, CK-MB, and myoglobin can predict the risk of disease progression in patients." (PMID 34222669, 2021). "Utilizing antibody functionalizsed microtubules label‐free and microscope‐free detection of the heart attack marker Creatine Kinase‐MB, as well secondary antibodies in nm concentration is demonstrated." (PMID 40237207, 2025). "cTnI is considered the gold-standard biomarker for diagnosing myocardial infarction due to its superior specificity and sensitivity compared to older markers such as CK-MB and myoglobin, both of which have been largely supplanted in contemporary practice." (PMID 41480420, 2025). "As a cardiac biomarker, myoglobin is important due to its rapid release into the bloodstream within 1–3 h after the onset of myocardial infarction (MI), peaking around 6–9 h." (PMID 39273041, 2024). "The LOD was 2.1 pg/mL when evaluated in PBS and 14 pg/mL when evaluated in artificial serum, which is below the threshold needed for the detection of a myocardial infarction (myoglobin: 70–200 ng/mL)." (PMID 37420790, 2023). "Typical cardiac biomarkers consisting of CRP, TNFα, CA-125, cTnI, cTnT, myoglobin, and CK-MB have an important role in diagnosing myocardial infarction (AMI)." (PMID 36832048, 2023). "Creatine kinase (CK) and its MB isoenzyme (CK-MB) are the most commonly used serological biomarkers for the diagnosis of myocardial infarction." (PMID 38089618, 2023). "Myoglobin is a protein found in muscle tissues and is released into the bloodstream in case of muscle lesion, such as a myocardial infarction." (PMID 38137422, 2023). "Under normal circumstances, myoglobin is excreted through kidneys, and it returns to the normal range within 20–30 h in patients with acute myocardial infarction." (PMID 38264034, 2023). "CK-MB had an AUC of 0.84, and myoglobin had an AUC of 0.79 in the early diagnosis of myocardial infarction in patients with chest pain." (PMID 36051380, 2022). "So, for example, with the development of myocardial infarction, the concentration of low molecular weight cardiac markers (myoglobin) in blood serum rises much earlier than the concentration of high molecular weight cardiac markers (lactate dehydrogenase-1)." (PMID 35402607, 2022). "During a heart attack or severe muscle damage, myoglobin is rapidly released in the body to constitute itself as a precise biomarker of acute myocardial infarction." (PMID 35897951, 2022).
myocardial infarction (continued). "For example, Mb is a biomarker for acute myocardial infarction, high sensitivity for the detection of myoglobin based on its intrinsic SERRS was achieved by a 3D Ag anisotropic nanopinetree array." (PMID 36430342, 2022). "In summary, pure and Cr-doped ZnO NPs were synthesized via the facile sol-gel method and used to fabricate high-sensitive and selective acute myocardial infarction myoglobin biomarkers." (PMID 36004981, 2022). "This is due to the fact that myoglobin molecules are small and can be released at the initial stages of ischemia during the development of myocardial infarction (when the plasma membrane of myocardial cells is still relatively insignificantly damaged)." (PMID 35402607, 2022). "In this article, we describe the fabrication and characterization of a sensor for acute myocardial infarction that detects myoglobin biomarkers using chromium (Cr)-doped zinc oxide (ZnO) nanoparticles (NPs)." (PMID 36004981, 2022). "Herein, we report the fabrication and characterization of a myoglobin biomarker sensor to detect acute myocardial infarction using chromium (Cr)-doped zinc oxide (ZnO) NPs." (PMID 36004981, 2022). "Due to substantial levels of myoglobin in skeletal muscles, myoglobin is an early indication of acute myocardial infarction but lacks cardiac specificity." (PMID 36264449, 2022). "In this study, using pure and copper-doped titanium dioxide (Cu-TiO2) nanostructures as the base matrix, enzyme-less label free myoglobin detection to identify acute myocardial infarction was performed and presented." (PMID 36551118, 2022). "Myoglobin is a crucial cardiac biomarker for early detection and diagnosis of myocardial infarction as it released into the bloodstream once there is an incidence of cardiac muscle injury." (PMID 33799932, 2021). "In this context, Mn-doped zinc oxide nanoparticles (Mn-ZnO NPs) were spatially designed to detect early signs of acute myocardial infarction by monitoring myoglobin content." (PMID 33799932, 2021). "Mair J, Morandell D, Genser N, Lechleitner P, Dienstl F, Puschendorf B. Equivalent early sensitivities of myoglobin, creatine kinase MB mass, creatine kinase isoform ratios, and cardiac troponins I and T for acute myocardial infarction." (PMID 34320090, 2021). "Research on myocardial infarction searched C-reactive protein, myoglobin, myeloperoxidase, creatine phosphokinase, creatin kinase MB, cardiac troponin T and cathepsin-L, all reporting statistically significant result." (PMID 32040469, 2020). "BNP and NT-proBNP were evaluated—along with myocardial injury markers cardiac troponin T (cTnT), myoglobin, and creatine kinase MB (CK-MB)—in acute myocardial infarction patients." (PMID 31013779, 2019). "Myoglobin (Mb) is one of the early biomarker levels which increases sharply from 90 pg/mL to 250 ng/mL within 90 min after acute myocardial infarction (AMI), playing a major role in urgent diagnosis of CVD." (PMID 29857573, 2018). "Compared to myoglobin and creatine-kinase-MB, cTnI is more sensitive and specific to acute myocardial infarction (AMI)." (PMID 29735888, 2018). "Its main advantage lies in its quick release after an ischemic event: in human patients with myocardial infarction, myoglobin levels rise within 2 h, peak between 6 and 9 h and return to normal within 24 to 36 h." (PMID 29143665, 2017). "Then 1975 saw the beginning of assays for the detection of monoclonal antibodies with the development of serum myoglobin to detect presence of myocardial infarction." (PMID 29143665, 2017). "Such a sensor is successfully fabricated at low cost and applied for the label-free binding assay of myoglobin for potential early diagnosis of myocardial infarction." (PMID 27006922, 2013). "It is well known that certain proteins, including myoglobin, called serum cardiac markers, are released into the bloodstream in large quantities from necrotic cardiac muscle cells after myocardial infarction." (PMID 22435364, 2012).